ADH4 (alcohol dehydrogenase 4 (class II), pi polypeptide)
Description:
Catalyzes the NAD-dependent oxidation of either all-trans-retinol or 9-cis-retinol. Also oxidizes long chain omega-hydroxy fatty acids, such as 20-HETE, producing both the intermediate aldehyde, 20-oxoarachidonate and the end product, a dicarboxylic acid, (5Z,8Z,11Z,14Z)-eicosatetraenedioate. Also catalyzes the reduction of benzoquinones.
Synonyms: ADH-2; HEL-S-4
Tractability: Small molecule: an approved drug acts on it; a structure with a bound ligand is known; it has a high-quality binding pocket; it belongs to a druggable protein family. PROTAC: a small molecule that binds it is known.
Target class: Enzyme; Oxidoreductase
Gene: Protein-coding gene on chromosome 4 (99,123,657 to 99,157,792, reverse strand). Ensembl gene ENSG00000198099.
Subcellular location: Cytoplasm
Subcellular location (Human Protein Atlas): Cytosol; Nucleoplasm
Pathways (Reactome):
Metabolism: Ethanol oxidation
Signal Transduction: RA biosynthesis pathway
Gene Ontology:
Molecular function: alcohol dehydrogenase (NAD+) activity; all-trans retinal binding; all-trans-retinol dehydrogenase (NAD+) activity; benzaldehyde dehydrogenase (NAD+) activity; NAD binding; protein binding; retinol binding; zinc ion binding; quinone reductase (NADPH) activity; aldose reductase (NADPH) activity; long-chain fatty aldehyde dehydrogenase (NAD+) activity; NADH dehydrogenase (quinone) (non-electrogenic) activity; oxidoreductase activity
Biological process: alcohol metabolic process; aldehyde metabolic process; fatty acid omega-oxidation; retinoid metabolic process; retinol metabolic process; alcohol catabolic process; formaldehyde catabolic process; quinone metabolic process
Cellular component: cytosol; cytoplasm
Genetic constraint (gnomAD): Loss-of-function variants: 22 observed, 29.18 expected, observed/expected ratio (o/e) 0.75, 90% interval 0.54 to 1.08. The upper end of that interval is the gene's LOEUF score, 1.08, which puts it in group 4 of 6, group 1 being the genes least tolerant of losing a copy. Missense variants: 450 observed, 435.81 expected, observed/expected ratio (o/e) 1.03, 90% interval 0.95 to 1.12. Synonymous variants: 164 observed, 151.75 expected, observed/expected ratio (o/e) 1.08, 90% interval 0.95 to 1.23.
Homologues: Orthologues: chimpanzee ADH4 (98% identical), macaque ADH4 (96% identical), dog ADH4 (81% identical), pig ADH4 (79% identical), rabbit ADH4 (76% identical), rat Adh4 (72% identical), mouse Adh4 (71% identical), tropical clawed frog adh4 (68% identical), zebrafish zgc:77938 (56% identical), zebrafish adh5l (55% identical), zebrafish adh8a (53% identical), zebrafish adh8b (52% identical), and 5 more. Paralogues in human: ADH5 (61% identical), ADH1B (60% identical), ADH1A (59% identical), ADH1C (59% identical), ADH6 (58% identical), ADH7 (57% identical), RTN4IP1 (22% identical), TP53I3 (20% identical), CRYZ (19% identical), SORD (19% identical), VAT1 (19% identical), VAT1L (18% identical), and 5 more.
Diseases named in the same sentence as ADH4 in open-access papers:
ADH4 is named in the same sentence as 47 diseases in open-access papers, as found by Europe PMC text mining. Sharing a sentence is not in itself a finding about the gene and the disease. The quoted sentences say what the papers report.
alcohol dependence (13 papers, 2007 to 2025). Physical and psychological dependence on alcohol. "The ADH4 gene encodes the alcohol dehydrogenase enzyme and variations in this gene are associated with alcohol dependence." (PMID 36358356, 2022). "Proper ADH4 functions are critical for alcohol metabolism, and functional changes in ADH4 and other alcohol dehydrogenase-related genes are associated with alcohol dependence or alcohol-induced medical diseases." (PMID 33557409, 2021). "In our previous studies, we reported positive associations between seven ADH4 polymorphisms and substance dependence [i.e., alcohol dependence (AD) and/or drug dependence (DD)] in European-Americans (EAs)." (PMID 18801187, 2008). "A study of 110 SNPs across all seven ADH genes demonstrated that variations in ADH4 most strongly affected risk for alcoholism in European-American families." (PMID 17718394, 2007). "An Italian study of 110 patients with episodic and chronic cluster headache and 203 controls found a significant genetic association between ADH4 SNP rs1126671, which has been associated with alcohol dependence and other addictive behaviors, and cluster headache." (PMID 39560176, 2025). "Increased ALDH2 expression, together with an ADH4 variant with lower binding affinity for alcohol, may represent risk factors for alcoholism in an adult FAS population." (PMID 38886650, 2024). "ADH4 has been associated with various disorders such as alcohol dependence." (PMID 35602603, 2022). "For example, ADH4 variants strongly affect alcoholism risk in populations of European descent." (PMID 17718394, 2007). "The alcohol dehydrogenase 4 (ADH4) gene encodes the class II alcohol dehydrogenase 4 pi subunit, a member of the alcohol dehydrogenase family associated with conditions such as alcohol dependence and cancer." (PMID 38654290, 2024). "Noteworthy variants also associated with alcohol dependence and consumption found to be enriched in the cohort included the risk alleles rs1614972 and rs698 in ADH1C, along with rs3762894 and rs671 in ADH4 and ALDH2, respectively." (PMID 38785976, 2024). "In particular, Adh4 was differentially methylated across the hypothalamus and WBCs of PAE animals, and has been previously associated with alcohol dependence and substance abuse." (PMID 30568673, 2018). "Previous studies have shown that interactions between SNPs across these genes are apparent in the risk of alcoholism, in particular between ADH1B and ADH7 and between ADH4 and ADH1A." (PMID 23166662, 2012).
liver cancer (7 papers, 2020 to 2025). An epithelial or non-epithelial malignant neoplasm that arises from the liver. "RT‐qPCR experiments demonstrated that in mouse liver cancer tissues, the expression levels of Spp2 and Adh4 were significantly lower in tumor tissues compared with adjacent nontumor tissues." (PMID 40018995, 2025). "Furthermore, 1000 lasso analysis also identified five genes: ADH4, AKR1B10, CEBPZOS, ENO1, and FOXN2, as the most stable prognosis-related genes associated with energy metabolism in liver cancer." (PMID 35602603, 2022). "And among genes related to gingivitis, ADH4 and FAM86C1 may be potential prognostic and diagnostic markers of liver cancer." (PMID 34026747, 2020). "Additionally, we investigated whether the core genes of HCCEvoSig were included in the CancerLivER database, which comprises over 594 liver cancer biomarkers, and found that four of 11 genes (ADH4, CYP2C9, SPP1 and SERPINE1) were included in the database." (PMID 40901047, 2025). "Based on the marker genes of this cluster and TCGA database data, the five most stable key genes (ADH4, AKR1B10, CEBPZOS, ENO1, and FOXN2) were identified as energy metabolism-related genes in liver cancer." (PMID 35602603, 2022). "ADH4 and ADH1A both belong to the alcohol dehydrogenase (ADH) superfamily and have revealed improved prognostic value in several cancer types, including non-small cell lung cancer, gastric cancer, and liver cancer." (PMID 36341373, 2022). "The results showed that UBE2C, PTTG1, TOP2A and SPP1 were positive, FCN3, SLC22A1, ADH4, CYP2C8, SLC10A1, and FBP1 were negative in liver cancer tissues." (PMID 38664521, 2024).
gastric cancer (5 papers, 2022 to 2025). A primary or metastatic malignant neoplasm involving the stomach. "However, excessive alcohol consumption significantly increases the risk of gastric cancer (GC), which is closely related to ADH4." (PMID 41031088, 2025). "UGT1A1, GPX3, ADH1B, and ADH4 can serve as cross pathway regulatory nodes and can be integrated into a “metabolic immune prognostic model” in the future to optimize precision treatment strategies for gastric cancer." (PMID 41031088, 2025). "The genes CLDN3, ADH4, and TFF3 have all been implicated in the development of gastric cancer." (PMID 37153834, 2023). "These key genes (UGT1A1, ADH4, ADH1B, CYP19A1, and GPX3) are crucial for the construction of our gastric cancer (GC) prognostic model." (PMID 41031088, 2025).
hepatocellular carcinoma (5 papers, 2021 to 2024). A malignant tumor that arises from hepatocytes. "This study identified a predictive signature comprising two specific hepatocyte genes, ADH4 and LCAT, which have been linked to the prognosis of hepatocellular carcinoma (HCC) and are considered protective factors." (PMID 38654290, 2024). "Alcohol Dehydrogenase 4 (ADH4) is a well-known prognostic protein biomarker for predicting the survival outcomes of patients with hepatocellular carcinoma whose expression is regulated by miR-664a-3p, which is upregulated in HCC." (PMID 36553522, 2022). "ADH4, a critical member of the ADH family, is a well-known prognostic biomarker for hepatocellular carcinoma and is involved in the metabolism of ethanol and retinol." (PMID 38589566, 2024). "On the other hand, there are only two reports on regulation of alcohol dehydrogenase (ADH) by miRNA: in human hepatoma cells, miR-1301-3p suppressed expression of ADH6, while miR-148a-3p promoted ADH4 expression." (PMID 34441974, 2021). "In human hepatoma cells, expression of ADH6 is reportedly suppressed by miR-1301-3p, while expression of ADH4 was increased by miR-148a-3p." (PMID 34441974, 2021).
esophageal cancer (3 papers, 2016 to 2022). A primary or metastatic malignant neoplasm involving the esophagus. "Only four ARSA SNPs were found in the database for East Asia, one of which was rs3805322, a variant in alcohol dehydrogenase 4 (ADH4) associated with an increased chance of esophageal cancer." (PMID 36011383, 2022). "Differential expression of ADH4 between tumor and normal tissues in patients with non-small cell lung cancer has been observed, and can be used as a prognostic marker in patients with esophageal cancer." (PMID 35602603, 2022).
lung carcinoma (3 papers, 2021 to 2024). "For lung cancer patients, high expression of ADH1B, ADH1C, ADH4, and ADH5 genes can achieve a better prognosis." (PMID 36212135, 2022).
vitamin A deficiency (3 papers, 2012 to 2024). Deficiency of vitamin A due to malnutrition, malabsorption, or dietary lack. "ADH4 knockout mice were susceptible to vitamin A deficiency during gestation and had lower fertility survival rate." (PMID 38374122, 2024). "Studies on mice with targeted Adh1 and Adh4 genes indicated that ADH1 provides considerable protection against vitamin A toxicity, whereas ADH4 promotes survival during vitamin A deficiency." (PMID 36837811, 2023). "In adult mice, ADH1 provides considerable protection against vitamin A toxicity whereas ADH4 promotes survival during vitamin A deficiency, a difference which illustrates distinct physiological functions for these two enzymes in retinol metabolism." (PMID 22319578, 2012).
Cluster headache (2 papers, 2018 to 2025). A type of headache characterized by repeated attacks of unilateral pain lasting 15 to 180 minutes and associated with local autonomic signs. "The attempt to further replicate the association between rs1800759 and rs1126671 polymorphisms of ADH4 and cluster headache failed in a large Swedish case-control cohort study of 390 cases and 389 controls." (PMID 39560176, 2025). "An examination of the data from included studies showed that the association between ADH4 and cluster headache risk was confirmed only in two Italian cohorts but not in other populations." (PMID 39560176, 2025). "The associations were also not supported in a subsequent Chinese population based case-control study suggesting that rs1126671 and rs1800759 polymorphisms of ADH4 gene are not genetic risk factors for cluster headache in the Chinese Han population." (PMID 39560176, 2025). "Therefore, ADH4 gene which is located on chromosome 4q22-4q23 is of special interest in the pathophysiology of cluster headache." (PMID 39560176, 2025).
drug dependence (2 papers, 2008 to 2025). "Alcohol is metabolized by alcohol dehydrogenase and genetic variants within alcohol dehydrogenase 4 (ADH4) gene have been associated with alcohol and drug dependence." (PMID 39560176, 2025).
Hypertension (2 papers, 2018 to 2023). The presence of chronic increased pressure in the systemic arterial system. "After CoxBoost processing, 10 variables remained as significant predictors of LD, including ADH4, hypertension, sex, fever, ANGL3, cough, feebleness, smoking, Hepatis B virus (HBV), and chest computed tomography (CT)." (PMID 36261228, 2023).
alopecia (1 paper, 2023). Hair loss usually from the scalp. "B6 substrains are prone (as a strain specific lesion) to develop what is known as B6 alopecia and dermatitis or B6 ulcerative dermatitis due to hypomorphic mutations in alcohol dehydrogenase 4 (Adh4)." (PMID 37796769, 2023).
angiomyolipoma (1 paper, 2021). A neoplasm with perivascular epithelioid cell differentiation often associated with tuberous sclerosis. "Just as in the TSC2-/- angiomyolipoma cell line S102, in the primary LAM lung tissue derived cell lines the expression of ADH1, ADH4 and ALDH1A1-2-3 showed the same pattern." (PMID 34178631, 2021).
breast carcinoma (1 paper, 2024). "ADH4 on the other hand, was shown to be significantly very high in the age group of 40–70 years of breast cancer patients." (PMID 38173442, 2024). "ADH4 on the other hand, was shown to be significantly very high in the age set of 40–70 years of breast cancer patients." (PMID 38173442, 2024).
colorectal cancer (1 paper, 2020). A primary or metastatic malignant neoplasm that affects the colon or rectum. "The expression of selected genes related to MG degradation III (AKR1B10, AKR1C2 and ADH4), glyoxalase system (GLO1 and HAGH), glucose transport (SLC2A1 and SLC5A1) and colorectal cancer-associated genes (AREG, CXCL8 and CEACAM1) were quantitated using qRT-PCR." (PMID 32561807, 2020).
Depression (1 paper, 2025). "In the Depression-GSE169459 validation set, the AUC values were BHLHE41 (0.8667), EPCAM (0.8667), ADH4 (0.5333), GSTM2 (0.9333), and GADD45G (0.8667)." (PMID 40508038, 2025). "Least absolute shrinkage and selection operator (LASSO) regression identified five candidate genes (BHLHE41, EPCAM, ADH4, GSTM2, GADD45G) from the Depression and BC datasets." (PMID 40508038, 2025). "In the Depression-GSE76826 dataset, the area under the curve (AUC) values were BHLHE41 (0.8333), EPCAM (0.7500), ADH4 (0.7500), GSTM2 (0.8333), and GADD45G (0.8500)." (PMID 40508038, 2025).
diabetic neuropathy (1 paper, 2023). A chronic, pathological complication associated with diabetes mellitus, where nerve damages are incurred due to diabetic microvascular injury involving small blood vessels that supply these nerves, resulting in peripheral and/or autonomic nerve dysfunction. "For diabetic neuropathy, gene GFY (rs4802605), ADH4 (rs4148883), LRFN2 (rs61731010), PKHD1 (rs2499486), SLC11A1 (rs17235409), MATN4 (rs2072788), and PPARA (rs4253772) were associated or contributed to the biological relevance to the pathogenesis of the complication." (PMID 37033211, 2023).
glioma (1 paper, 2024). A benign or malignant brain and spinal cord tumor that arises from glial cells (astrocytes, oligodendrocytes, ependymal cells). "ADH4, DHRS3, LRAT, RDH10, RDH12, and RDH5 were higher expressed in the high-glioma-risk group while DHRS9 was lower expressed." (PMID 39465792, 2024). "Ultimately, ADH4, DHRS3, DHRS9, LRAT, RDH10, RDH12, and RDH5 were selected as prognostic genes for building an RA metabolism–related prognostic signature with glioma." (PMID 39465792, 2024). "We identified 7 promising prognostic genes (ADH4, DHRS3, DHRS9, LRAT, RDH10, RDH12, and RDH5) within glioma and developed a prognostic model with significant predictive accuracy." (PMID 39465792, 2024). "The prognostic signature comprised of ADH4, DHRS3, DHRS9, LRAT, RDH10, RDH12, and RDH5 based on RA metabolism was established, which provided a theoretical basis and reference value for the research of glioma." (PMID 39465792, 2024).
Hepatic steatosis (1 paper, 2022). Steatosis is a term used to denote lipid accumulation within hepatocytes. "ADH4, which is considered a liver marker related to lipogenesis and lipid regulation, has an important role in the prevention of hepatic steatosis." (PMID 36421714, 2022).
non-alcoholic fatty liver disease (1 paper, 2023). "MR studies have provided evidence that non-alcoholic fatty liver disease (NAFLD) raises levels of ADH444, therefore weight loss reducing ADH4 could be an indicator of an improvement in liver function." (PMID 38030643, 2023).
osteoporosis (1 paper, 2024). A condition of reduced bone mass, with decreased cortical thickness and a decrease in the number and size of the trabeculae of cancellous bone (but normal chemical composition), resulting in increased fracture incidence. "Our study performed a comprehensive analysis of important EMGs in osteoporosis and developed a diagnosis signature consisting 5 EMGs, including B4GALT4, ADH4, ACAD11, B4GALT2, and PPP1R3C with a relative higher AUC." (PMID 38589566, 2024). "Overall, this study constructed a model that can predict the incidence of osteoporosis and identified B4GALT4, ADH4, ACAD11, B4GALT2, and PPP1R3C as potential biomarkers for osteoporosis development." (PMID 38589566, 2024). "B4GALT4, ADH4, ACAD11, B4GALT2, and PPP1R3C may be valuable biomarkers for the development of osteoporosis." (PMID 38589566, 2024). "Thus, we propose that B4GALT4, ADH4, ACAD11, B4GALT2, and PPP1R3C are involved in the development of osteoporosis, potentially by modulating metabolic pathways." (PMID 38589566, 2024).
substance dependence (1 paper, 2008). The psychological or physiological need to take a substance in order to experience its effects or to avoid the effects of its absence. "The most powerful HWD test suggests that the ADH4 variant (rs2226896) might play an important role in risk for substance dependence (including AD and DD) in AAs, probably via a recessive genetic mechanism." (PMID 18801187, 2008). "However, neither allelewise nor genotypewise case-control comparisons showed any significant association between ADH4 variation and substance dependence." (PMID 18801187, 2008). "In the present study, we address the relationship between ADH4 variation and substance dependence in an African-American (AA) population, and report evidence that supports an association between a different ADH4 polymorphism (rs2226896) and these phenotypes in AAs." (PMID 18801187, 2008). "ADH4 variation might play a role in risk for substance dependence in AAs, potentially via a recessive mechanism." (PMID 18801187, 2008). "Two family-based association study methods, i.e., TDT and FBAT, were applied to test the relationship between ADH4 variation and substance dependence in Sample 3 (112 small nuclear families) and in Sample 4 (632 pedigrees), respectively." (PMID 18801187, 2008).
systemic lupus erythematosus (1 paper, 2016). An autoimmune multi-organ disease typically associated with vasculopathy and autoantibody production. "Alcohol dehydrogenase 4 (ADH4) was involved in the most pathways (9 pathways) and Systemic lupus erythematosus pathway accounted for the most differentially expressed proteins (15 proteins)." (PMID 27485544, 2016).